IGF1R (insulin like growth factor 1 receptor)
Diseases named in the same sentence as IGF1R in open-access papers (continued):
Sharing a sentence is not in itself a finding about the gene and the disease.
breast cancer (continued). "Nevertheless, the use of a specific antibody targeting IGF1R in neuroblastoma and breast cancer xenograft models showed an antitumor activity, associated with a decrease in glucose uptake." (PMID 28969033, 2017). "The rs2016347 T allele is common in many ethnicities and is likely functional, as recent studies have associated this variant with lower normal tissue expression of IGF1R mRNA and better treatment responses and patient survival from HR+ breast cancer." (PMID 28822014, 2017). "In conjunction with previously reported breast cancer risk biomarkers by our group of investigators, such as IGF1R and Ki67, these results reinforce a new paradigm of predicting breast cancer risk by incorporating molecular markers." (PMID 28253895, 2017). "We examined the associations of breast cancer risk factors with estrogen receptor (ER), progesterone receptor (PR), insulin-like growth factor-1 receptor (IGF-1R), and Ki67 expression in normal breast tissue." (PMID 28979927, 2017). "Since IGF1R is associated with uPAR and co-overexpressed in breast cancer, here, it was downregulated in combination with uPAR and further analysed to demonstrate a direct interaction of both receptors." (PMID 27502396, 2016). "IGF1R overexpression has been implicated to play an important role in the development of breast cancer and the crosstalk between IGF1R and estrogen signaling has been well established in malignant breast tissue." (PMID 27964748, 2016). "While epithelial breast cancer cells commonly overexpress IGF-1R, surrounding tumor-associated stroma provides a rich source of IGF-2." (PMID 27765027, 2016). "Taken together, our data highlight the activation of IGF1R/p110β/AKT/mTOR as a mechanism of resistance to BYL719 in PIK3CA-mutated breast cancer cells." (PMID 27048245, 2016). "Immunohistochemical analysis of IGF1R levels in breast tumor specimens derived from BRCA1/BRCA2 mutation carriers, compared to matched sporadic breast cancer patients, revealed higher IGF1R levels in tumors of BRCA mutation carriers." (PMID 27446805, 2016). "To further understand the underlying mechanism of the decreased tumor latency by IGF1 and X10, we determined the expression of proteins in the main signaling pathways associated with IR and IGF1R signaling as well proteins used in breast cancer classification." (PMID 25848982, 2015). "BRCA1 has been shown to directly affect the IGF-1R pathway and studies have suggested that BRCA1/2 deficient breast cancer cells are associated with elevated expression of Insulin like growth factor-1 receptor (IGF-1R)." (PMID 26510816, 2015). "The type 1 IGF receptor (IGF-1R) is often overexpressed in breast cancer, and this overexpression has been associated with worse prognosis and shorter disease-free survival." (PMID 26536657, 2015). "IGF1R was associated also with favorable prognosis in breast cancer, non small cell lung cancer, soft tissue sarcoma and classical Hodgkin’s lymphoma." (PMID 25786252, 2015). "The expression and role of IGF1R in various breast cancer subtypes, and in particular its role in causing resistance to targeted therapies, has been extensively studied." (PMID 25964777, 2015). "On the contrary, rare studies reveal that high IGF1R mRNA and phosphorylated IGF1R/IR are associated with a poor prognosis, whatever the molecular subtype of breast cancer." (PMID 26449867, 2015). "Insulin-like growth factor 1 receptor (IGF1R) is another gene associated with both breast cancer and prostate cancer and polymorphisms in the IGF1R receptor are found which cause instability of the receptor protein." (PMID 26236721, 2015). "The SNPs of IGF1R in the breast cancer subjects was positively associated with subsequent risk and women with IGF1R SNPs were at higher risk of developing breast cancer." (PMID 24392142, 2014). "We investigated the genetic variations across the IGF1R polymorphism and the risk of breast cancer risk in Korean women." (PMID 24392142, 2014).
breast cancer (continued). "This study allowed us to evaluate the SNPs and haplotypes in the IGF1R gene associated with the risk of breast cancer." (PMID 24392142, 2014). "Total fifty one SNPs in the IGF1R gene were examined for association with breast cancer in the study." (PMID 24392142, 2014). "With respect to the association of IGF-1R with breast cancer outcome, discordant results have been published." (PMID 24467828, 2014). "Overall, these results confirmed a significant association between IGF1R SNPs and the risk of breast cancer." (PMID 24392142, 2014). "Four IGF1R SNPs (rs8032477, rs12439557, rs11635251, and rs12916884) were found to be associated with breast cancer risk in the study populations as well as significant in combined analyses (p = 0.0003)." (PMID 24392142, 2014). "We analyzed the association between IGF1R SNPs and breast cancer risk following multiple testing corrections." (PMID 24392142, 2014). "This case-control study identifies tagSNPs in the IGF1R gene and demonstrates their statistically significant associations with the risk of breast cancer risk in a population of Korean women." (PMID 24392142, 2014). "These seven IGF1R SNPs (rs4966007, rs8028620, rs4966009, rs8027457, rs4966012, rs1574213, and rs11630479) were likely to be associated with breast cancer risk." (PMID 24392142, 2014). "Since IGF axis appears to play important roles in determining both tumor growth and progression in breast cancer, we aimed to characterize the genetic variations across the IGF1R polymorphism and the risk of breast cancer risk in Korean women." (PMID 24392142, 2014). "An elevation in the expression of IGF1R in normal breast tissue is known to be associated with an increase in the risk of subsequent breast cancer." (PMID 25403427, 2014). "Cytoplasmic IGF1R expression in epithelial cells of normal breast tissue has been positively associated with subsequent risk of breast cancer." (PMID 24392142, 2014). "A significant association with breast cancer risk was found in analysis showing association between IGF1R haplotypes and breast cancer risk." (PMID 24392142, 2014). "Overall, this case-control study demonstrates statistically significant associations between breast cancer risk and polymorphisms in IGF1R gene." (PMID 24392142, 2014). "The expression patterns of IGF1R in epithelial cells of normal terminal duct lobular units in benign breast biopsies were found to be associated with an increased risk of subsequent breast cancer." (PMID 24392142, 2014). "Haplotype analysis of the association between IGF1R under three genetic models and the risk of breast cancer." (PMID 24392142, 2014). "The IGF 1 receptor (IGF1R) overexpression has been associated with a number of hematological neoplasias and solid tumors including breast cancer." (PMID 24392142, 2014). "Seven of the 51 IGF1R SNPs were in LD and in one haplotype block, and were likely to be associated with breast cancer risk." (PMID 24392142, 2014). "Epigenetic silencing of miR-375 causes the upregulation of IGF1R, which at least partially underlies trastuzumab resistance of breast cancer cells." (PMID 24571711, 2014). "Han-Sung Kang found that seven of the 51 IGF1R SNPs were in LD (linkage disequilibrium) and in one haplotype block, and were likely to be associated with breast cancer risk." (PMID 25003827, 2014). "Aberrant expression of components of the IGF1R pathway is associated with better clinical outcomes in women with luminal A and B, node positive, early breast cancer." (PMID 24637962, 2014). "A case-control study was conducted to first comprehensively evaluate IGF1R genetic variants in relation to breast cancer risk and then to assess any promising associations among study population." (PMID 24392142, 2014).
breast cancer (continued). "Increased expression of IGFBP2 caused by loss of miR-126 was found to promote breast cancer cell metastasis by recruitment of endothelial cells to the cancer site through up-regulating the insulin growth factor 1 receptor (IGF1R) signaling pathway." (PMID 24069370, 2013). "Expression of IGF-1R is known to be increased in human breast cancers and associated with increased cellular proliferation." (PMID 24156623, 2013). "The Insulin Growth Factor 1 Receptor (IGF1R) has been associated with the growth, invasion, and metastasis in breast cancer patients and is over-expressed in 50%–75% of TNBCs." (PMID 24244833, 2013). "In a preclinical study, co-expression of HER2 and IGF1R in breast cancer cells resulted in loss of sensitivity to trastuzumab treatment, whereas blocking ligand activation of IGF1R restored trastuzumab-related growth inhibition." (PMID 22649737, 2012). "Remarkable activity was seen in breast cancer patients in a phase I dose finding study of oral mTOR inhibitor ridaforolimus associated to IGF-1R monoclonal antibody, MK-0646 (dalotuzumab)." (PMID 22415797, 2012). "Other critical factors such as p-STAT5, p-STAT3, p-IGF-1R, Jak2 and Brk causing breast cancer were also suppressed by HSE." (PMID 22792362, 2012). "A study in breast cancer demonstrated that increasing BMI was positively associated with increased IGF-1R expression in both normal mammary gland tissue and breast cancer tissue." (PMID 21696633, 2011). "Herein we have shown that there is a causative mechanism of the IGF-1/IGF-1R axis in the antiestrogen drug resistance of breast cancer cells." (PMID 21595894, 2011). "Although initially thought to correlate with estrogen receptor (ER) expression, IGF-1R has recently been implicated in multiple breast cancer subtypes and its expression correlates with poor prognoses." (PMID 20668531, 2010). "Both IGF1R overexpression and IRS1 overexpression have been associated with breast cancer development, and IGF1R is overexpressed in a majority of breast tumors." (PMID 19843326, 2009). "Among BRCA1 carriers, significant associations were found between risk of breast cancer and LD blocks in IGF1R (global P = 0.011 for LD block 2 and global P = 0.012 for LD block 11)." (PMID 19843326, 2009). "Importantly, dysregulation of the IGF-1/IGF-1R axis has been increasingly implicated in therapy resistance in breast cancer." (PMID 41157306, 2025). "Moreover, univariate COX analysis showed that the factors including tumor stage, N stage, CD163 expression, CXCL1 expression, HMGB1 expression, and IGF1R expression were significantly associated with breast cancer prognosis." (PMID 39394189, 2024). "Indeed, high levels of IGF-1R are associated with a worse disease prognosis in breast cancer patients, as assessed through a computational analysis of cancer genomics information available in public databases." (PMID 36612320, 2023). "A major question that arises from the METABRIC WGCNA is whether there is a causative relationship between IGF1R expression and associated gene alterations and, ultimately, phenotype of breast cancer." (PMID 36568144, 2022). "Importantly, the mouse modeling data aligns with the human gene expression and pathway analyses and provides a basis for understanding why loss of IGF1R in human breast cancers is associated with a worse outcome." (PMID 36568144, 2022). "In breast cancer, the IGF1R pathway is linked to estrogen-dependent signaling." (PMID 36093095, 2022). "The findings from human and mouse support the hypothesis that low expression of IGF1R could be used to identify gene signatures associated with aggressive breast cancers." (PMID 36568144, 2022). "Prior reports have also linked E-cadherin and IGF1R in breast cancers." (PMID 36568144, 2022). "IGF-1R expression is associated with worse prognosis in breast cancer." (PMID 36291900, 2022).
breast cancer (continued). "The insulin growth factor receptor (IGF1R) is a tyrosine kinase receptor that has been linked to the genesis and progression of breast cancer tumors, and its IGF1R expression is associated with clinical–pathological factors in breast carcinomas." (PMID 36430763, 2022). "Interestingly, high IGF-1R expression appears to be associated with lower metastatic potential in breast cancer." (PMID 33451345, 2021). "Since African American breast cancer patients have upregulation of the IGF-1R signaling pathway, which is associated with poor radiation response, identifying a mechanism to downregulate the pathway could optimize radiation response." (PMID 35008602, 2021). "Therefore, IR can compensate for the loss of IGF1R and stimulate growth in endocrine-resistant breast cancer cells." (PMID 33429867, 2021). "Vitamin D may help address the immune dysfunction associated with IGF-1R dysregulation seen in AA breast cancer patients." (PMID 35008602, 2021). "Similarly, high IGF-1R expression by IHC has previously been associated with ER positivity in breast cancer." (PMID 32393319, 2020). "We additionally explored whether expression of the IR and IGF-1R in the breast cancer cells was associated with race and worse breast cancer prognosis." (PMID 32393319, 2020). "Recent findings from the California Teachers Study demonstrated that among women with a history of preeclampsia, those carrying the TT genotype of a specific functional IGF1R SNP (rs2016347) had a decrease in risk for estrogen receptor-positive breast cancer of 74% when compared to the GG genotype." (PMID 31687025, 2019). "Our group has reported that nuclear IGF-1R is detectable in pre-invasive lesions and several types of invasive malignancy including prostate, renal and breast cancers, and is associated with adverse prognosis in renal cancer and advanced tumor stage in prostate cancer." (PMID 31416218, 2019). "Finally, the detection of IGF1R‐expressing CTCs is associated with a favorable outcome in CTC(+) patients with early breast cancer." (PMID 28766847, 2018). "Importantly, we show that IGF1R expression in CTCs is associated with improved prognosis in early breast cancer." (PMID 28766847, 2018). "A recent meta-analysis of ten independent studies evaluating cytoplasmic and membrane staining of IGF1R in breast cancer patients concluded that IGF1R was associated with better outcome in hormone receptor positive cancers, but with poor survival in triple-negative breast cancers." (PMID 28030849, 2017). "Ongoing investigation in our laboratory has motivated us to hypothesize that the molecular composition of plasma membrane microdomains associated with IGF-1R network receptors might dictate the tumorigenic activity of IRS-1/2 in breast cancer." (PMID 29152592, 2017). "Prior studies including ours have suggested that expression levels of estrogen receptor (ER), progesterone receptor (PR), IGF-1 receptor (IGF-1R), and Ki67 in cancer-free breast tissue may be associated with subsequent breast cancer risk." (PMID 28979927, 2017). "Importantly, elevated IGF1R expression is prevalent in women who are at risk for developing breast cancer subtypes with distinctive aggressive phenotypes." (PMID 28947975, 2017). "A study of genetic variations across IGF1R SNPs and the risk of breast cancer risk in Korean females showed that among 51 IGF1R SNPs, 5 intron-located SNPs (rs8032477, rs7175052, rs12439557, rs11635251, and rs12916884) were associated with a decreased risk of breast cancer." (PMID 27144430, 2016). "Indeed, some studies showed that IGF1R negativity and down-regulation was associated with a worse prognosis in tamoxifen-treated postmenopausal breast cancer and correlated with aggressive features such as poor differentiation and high proliferation." (PMID 26449867, 2015). "Analysis of the association between IGF1R gene under additive model and the risk of breast cancer." (PMID 24392142, 2014).
breast cancer (continued). "IGF1R allele frequencies and genotype distribution in breast cancer controls and cases." (PMID 24392142, 2014). "Although this study reports genetic polymorphisms on the IGF1R on breast cancer in Korea for the first time, the findings need to be validated in further studies with larger sample size or in meta-analyses, which is also aimed in our laboratory for years to come." (PMID 24392142, 2014). "Considering the status of IGF1R polymorphisms our results may help in improving the ability to develop effective treatment modalities with reference to associated risk breast cancer." (PMID 24392142, 2014). "We genotyped total 51 SNPs in the IGF1R gene and examined for association with breast cancer." (PMID 24392142, 2014). "Among 51 IGF1R SNPs, five intron located SNPs (rs8032477, rs7175052, rs12439557, rs11635251 and rs12916884) with homozygous genotype (variant genotype) were associated with decreased risk of breast cancer." (PMID 24392142, 2014). "Seven IGF1R SNPs in intron region (rs8032477, rs4966035, rs2684803, rs1546713, rs7166558, rs11635251), and one in coding region (rs12916884) were significantly associated with the breast cancer risk." (PMID 24392142, 2014). "Also four IGF1R SNPs with homozygous genotype (variant genotype) had decreased risk of breast cancer." (PMID 24392142, 2014). "In more detail, we could show that IGF1R negativity was associated with shorter distant disease-free survival (DDFS) in a cohort of postmenopausal women with stage II breast carcinoma." (PMID 25362932, 2014). "Our data provide evidence that the IGF-1/IGF-1R signaling axis may play a causal role in antiestrogen resistance of breast cancer cells, despite continuous suppression of ER transcriptional function by antiestrogens." (PMID 21595894, 2011). "Moreover, in women, elevated LIP or IGF-1R expression are independently associated with breast cancer." (PMID 21854628, 2011). "High expression of IGF-1R has been demonstrated in most primary human breast cancers when compared with normal or benign breast tissue, and hyperactivation of IGF-1R in breast cancer has been linked with increased radioresistance and cancer recurrence at the primary site." (PMID 16457688, 2005). "Interestingly, the pathways upregulated in both patient and mouse tumors with reduced IGF1R are important for response to stress signaling and immune cell evasion supporting our prior findings that loss of IGF1R promotes cell stress in human breast cancer cells." (PMID 36568144, 2022). "Also, IRAIN, Linc00319, and DLEU1 through negatively regulating IGF-1R could cause breast cancer, cervical cancer, and hepatocellular carcinoma." (PMID 33768092, 2021). "We aimed to determine whether insulin resistance mediates in part the association between race and breast cancer prognosis, and if insulin receptor (IR) and insulin-like growth factor receptor (IGF-1R) expression differs between tumors from Black and White women." (PMID 32393319, 2020). "Additionally, some tissue-specific biomarkers have been associated with breast cancer risk in specific subsets of women, such as insulin-like growth factor 1 receptor (IGF1R), and more recently, the combination of Ki67 and estrogen receptor (ER) expression in a subset of women." (PMID 28253895, 2017). "However, in the present study, no prognostic significance was evaluated for the IGF1R so further study may help to explain the associations of IGF1R with breast cancer in individuals with different tumor subtypes." (PMID 24392142, 2014). "Modulating IGF-1R expression restored radiosensitivity in poly (ADP-ribose) polymerase (PARP) inhibitor-resistant breast cancer cells." (PMID 42095258, 2026). "The IGF-1R pathway interacts with key therapeutic targets such as Her2 and ER, thereby influencing breast cancer treatment." (PMID 41310487, 2025).